CBLB (Cbl proto-oncogene B)
Description:
E3 ubiquitin-protein ligase which accepts ubiquitin from specific E2 ubiquitin-conjugating enzymes, and transfers it to substrates, generally promoting their degradation by the proteasome. Negatively regulates TCR (T-cell receptor), BCR (B-cell receptor) and FCER1 (high affinity immunoglobulin epsilon receptor) signal transduction pathways. In naive T-cells, inhibits VAV1 activation upon TCR engagement and imposes a requirement for CD28 costimulation for proliferation and IL-2 production (By similarity). Also acts by promoting PIK3R1/p85 ubiquitination, which impairs its recruitment to the TCR and subsequent activation. In activated T-cells, inhibits PLCG1 activation and calcium mobilization upon restimulation and promotes anergy (By similarity). Involved in LAG3-mediated inhibition of TCR signaling: following ligand-binding to LAG3, catalyzes 'Lys-63'-linked ubiquitination of LAG3, unleashing the LAG3 C-terminus from the membrane, and initiating a signaling that prevents TCR activation. In B-cells, acts by ubiquitinating SYK and promoting its proteasomal degradation (By similarity). Slightly promotes SRC ubiquitination. May be involved in EGFR ubiquitination and internalization. May be functionally coupled with the E2 ubiquitin-protein ligase UB2D3. In association with CBL, required for proper feedback inhibition of ciliary platelet-derived growth factor receptor-alpha (PDGFRA) signaling pathway via ubiquitination and internalization of PDGFRA (By similarity).
Synonyms: RNF56; Nbla00127; Cbl-b; ADMIO3
Tractability: Small molecule: a structure with a bound ligand is known; a high-quality ligand is known. Antibody: its Gene Ontology location is reachable by antibodies, with medium confidence. PROTAC: UniProt records ubiquitination sites on it; ubiquitination databases record sites on it; its protein half-life has been measured; a small molecule that binds it is known.
Target class: Enzyme; Transferase
Gene: Protein-coding gene on chromosome 3 (105,655,461 to 105,869,552, reverse strand). Ensembl gene ENSG00000114423.
Subcellular location: Cytoplasm
Subcellular location (Human Protein Atlas): Cytosol; Nucleoplasm
Pathways (Reactome):
Immune System: Antigen processing: Ubiquitination & Proteasome degradation
Gene Ontology:
Molecular function: protein binding; ubiquitin protein ligase activity; receptor tyrosine kinase binding; zinc ion binding; calcium ion binding; metal ion binding; phosphotyrosine residue binding; ubiquitin-protein transferase activity
Biological process: negative regulation of T cell activation; negative regulation of T cell receptor signaling pathway; protein K63-linked ubiquitination; protein stabilization; negative regulation of epidermal growth factor receptor signaling pathway; NLS-bearing protein import into nucleus; regulation of platelet-derived growth factor receptor-alpha signaling pathway; signal transduction; cell surface receptor signaling pathway; protein ubiquitination; regulation of signaling
Cellular component: cytosol; plasma membrane; membrane raft; cytoplasm
Genetic constraint (gnomAD): Loss-of-function variants: 22 observed, 77.35 expected, observed/expected ratio (o/e) 0.28, 90% interval 0.2 to 0.41. The upper end of that interval is the gene's LOEUF score, 0.41, which puts it in group 1 of 6, group 1 being the genes least tolerant of losing a copy. Missense variants: 859 observed, 1,023.2 expected, observed/expected ratio (o/e) 0.84, 90% interval 0.79 to 0.89. Synonymous variants: 349 observed, 361.44 expected, observed/expected ratio (o/e) 0.97, 90% interval 0.88 to 1.05.
Cancer hallmarks: invasion and metastasis (suppresses); suppression of growth (promotes); escaping immune response to cancer (promotes)
Homologues: Orthologues: chimpanzee CBLB (99% identical), macaque CBLB (99% identical), rabbit CBLB (97% identical), dog CBLB (97% identical), pig CBLB (97% identical), rat Cblb (96% identical), mouse Cblb (95% identical), guinea pig CBLB (91% identical), tropical clawed frog cblb (78% identical), zebrafish cblb (66% identical). Paralogues in human: CBL (49% identical), CBLC (22% identical).
Diseases named in the same sentence as CBLB in open-access papers:
CBLB is named in the same sentence as 123 diseases in open-access papers, as found by Europe PMC text mining. Sharing a sentence is not in itself a finding about the gene and the disease. The quoted sentences say what the papers report.
breast carcinoma (25 papers, 2015 to 2024). "The E3 Ubiquitin Ligase Cbl-b, coded by oncogene CBLB, has been reported to affect cancer development and progression and has been proposed as a clinical biomarker in breast cancer." (PMID 36703164, 2023). "hsa-miR-27b-3p directly targets HSP90AA1 and Fzd7 in NSCLC, ROR1 in gastric cancer, and CBLB/GRB2 in breast cancer to suppresses cell proliferation, migration, invasion, and expression of MET." (PMID 34603447, 2021). "Next, we compared mRNA levels of these genes in tumor tissues and their matched adjacent normal tissues in breast cancer patients (n = 93) and found CBLB and GRB2 expression were significantly higher in tumor tissues." (PMID 29416005, 2018). "All these results suggested that miR-27b attenuated breast cancer cell resistance to PTX by repressing CBLB and GRB2." (PMID 29416005, 2018). "There is recently mounting evidence that CBLB expression may be useful as a prognostic factor in breast cancer." (PMID 36703164, 2023). "However, studies have suggested that the higher CBLB expression is related to the development of several malignant tumors, such as breast cancer, melanoma, head and neck cancer, and more." (PMID 38105184, 2023). "In breast cancers, CBLB was reported to regulate p-glycoprotein transporter function." (PMID 29416005, 2018). "Plenty of miRNA-mRNA axes, such as miR-34a-Notch1 axis, miR-125b-Sema4c axis, miR-181-Bcl-2 axis, and miR-27b/CBLB/GRB2 axis, were reported that regulated taxanes-resistance in breast cancer." (PMID 32974144, 2020). "Remarkably, our study indicated CBLB and GRB2 were direct targets of miR-27b, and played important roles in miR-27b-mediated PTX sensitivity in breast cancers." (PMID 29416005, 2018). "Above results definitely indicated miR-27b negatively regulated CBLB and GRB2 by direct binding in breast cancer cells." (PMID 29416005, 2018). "The MTT assays showed downregulation of CBLB or GRB2 expression significantly inhibited cell proliferation, and increased cell sensitivity to PTX in breast cancer cells." (PMID 29416005, 2018). "Moreover, a significantly negative correlation between miR-27b and CBLB/GRB2 expression were found in tumor tissues of breast cancer patients (n = 93)." (PMID 29416005, 2018).
gastric cancer (20 papers, 2013 to 2024). A primary or metastatic malignant neoplasm involving the stomach. "It reported that CBLB regulated the sensitivity of cetuximab through ubiquitin-proteasome system in human gastric cancer cells." (PMID 29416005, 2018). "Another study also reported that downregulation of CBLB sensitized gastric cancer to rapamycin through PI3K/Akt pathway." (PMID 29416005, 2018).
Autoimmunity (19 papers, 2011 to 2024). The occurrence of an immune reaction against the organism's own cells or tissues. "We report homozygous germline disease-causing variants in CBLB in 3 unrelated patients with early-onset autoimmunity." (PMID 36006710, 2022). "Distinct homozygous mutations in CBLB were identified in 3 unrelated children with early-onset autoimmunity, one of whom also had chronic urticaria." (PMID 36006710, 2022). "Transgenic complementation with wild type CBLB greatly suppresses the development of the Komeda diabetes-prone phenotype, indicating that CBLB is a negative regulator of autoimmunity and a susceptibility gene for T1DM in the rat." (PMID 34006268, 2021). "Interestingly, genetic association studies link CBLB-polymorphisms with autoimmunity also in humans." (PMID 25815272, 2015). "The potential relevance of alterations in Cbl-b in autoimmunity is also supported by the finding that single nucleotide polymorphisms in the CBLB gene are associated with human autoimmune diseases such as systemic lupus erythematosus and multiple sclerosis." (PMID 28184224, 2017). "As a result, CBLB‐deficient T cells proliferate and synthesize cytokines following stimulation with suboptimal concentration of anti‐TCR antibody or in the absence of CD28 costimulation, and in turn, CBLB‐deficient mice are prone to autoimmunity." (PMID 27474268, 2016).
autoimmune disease (13 papers, 2014 to 2025). A disorder resulting from loss of function or tissue destruction of an organ or multiple organs, arising from humoral or cellular immune responses of the individual to their own tissue constituents. "Indeed, reduced expression of Cbl-b in PBMC, or more specifically in CD4+ T cells, was a common finding in several autoimmune diseases and CBLB mRNA levels in T cells were inversely correlated with relapse rates in multiple sclerosis patients." (PMID 25815272, 2015). "Thus, CBLB is a key gene of T1DM, and downregulated CBLB participating in the insulin signaling pathway may contribute to the autoimmune disease of T1DM." (PMID 34006268, 2021).
melanoma (11 papers, 2015 to 2024). A malignant, usually aggressive tumor composed of atypical, neoplastic melanocytes. "One of these mutational networks presented in melanoma was the one containing MET besides CARD11, CBLB, PPP6C and RAC1." (PMID 34885093, 2021).
lung carcinoma (10 papers, 2015 to 2024). "Entinostat can induce the expression of CBLB, a gene that is repressed by SALL4 in lung cancer cells, representing a potential mechanism for the sensitivity of SALL4-expressing lung cancer cells to this drug." (PMID 27705911, 2016).
cobalamin deficiency (7 papers, 2015 to 2021). "From the top candidate genes, we were initially interested in the methylmalonic aciduria (cobalamin deficiency) cblB type (MMAB) gene." (PMID 34750386, 2021). "Little is known about the association of the mevalonate kinase (MVK), methylmalonic aciduria (cobalamin deficiency) cblB type (MMAB) single nucleotide polymorphisms (SNPs) and serum lipid levels." (PMID 29050287, 2017). "MMAB [methylmalonic aciduria (cobalamin deficiency) cblB type] encodes a protein that catalyzes the conversion of vitamin B12 into adenosylcobalamin, an active coenzyme form of B12." (PMID 26308950, 2015). "Genes related to stress response (ceremide kinase like) and nutrient metabolism (phosphoenolpyruvate carboxy-kinase 1, methylmalonic aciduria [cobalamin deficiency] cblB type, glycine receptor alpha 2, solute carrier family 7 member 11, etc.)were also identified to be differentially expressed." (PMID 33152221, 2021).
methylmalonic acidemia (7 papers, 2018 to 2025). A genetically heterogenous inherited disorder characterized by abnormalities in the metabolism of lipids and proteins. "Several very rare conditions, including CACT deficiency, HLCSD, LCHADD, methylmalonic acidemia (CblB type), PTPS deficiency, and MAT I deficiency, were also identified in Louisiana." (PMID 41440808, 2025). "This variant is responsible for isolated methylmalonic acidemia due to a defect in the synthesis of adenosylcobalamin, cblB complementation type, with an autosomal recessive mode of inheritance." (PMID 37248539, 2023). "Methylmalonic acidemia cblB type (MMA cblB) is an autosomal recessive inborn error of amino acid metabolism that results in impaired synthesis of adenosylcobalamin, a cofactor of methylmalonyl-CoA mutase." (PMID 38444575, 2024). "These articles from 2002 and 2006 describe two individuals with methylmalonic acidemia (MMA) cblB type who each harbor the same three unphased heterozygous variants: p.Ala135Thr, NM_052845.4:p.Arg191Trp, and NM_052845.4:p.Tyr219Cys." (PMID 37443081, 2023). "WES data analysis revealed a homozygous variant, NM_052845.4 (MMAB):c.557G > A, p.Arg186Gln, in exon 7 of the gene, suggesting isolated methylmalonic acidemia, cblB type." (PMID 37248539, 2023). "OAs, almost equivalent to FAODs, represent the third most frequent class of IEMs in the Lombardy cohort, affecting 12.92% of the affected population, with methylmalonic acidemias (CblA/C, CblB/D and MUT) (1:22,900) and IVA (1:114,502) being the two most common types." (PMID 40407514, 2025). "Isolated methylmalonic acidemia (MMA) is caused by complete or partial deficiency of the enzyme methylmalonyl-CoA mutase (mut0 or mut– enzymatic subtype), a defect of its cofactor adenosyl-cobalamin (cblA, cblB, or cblD-MMA), or deficiency of the enzyme methylmalonyl-CoA epimerase." (PMID 33453710, 2021).
Methylmalonic aciduria (7 papers, 2015 to 2021). Increased concentration of methylmalonic acid in the urine. "Methylmalonic aciduria cblB type (MMA cblB, OMIM #251110) is an inherited rare disease caused by mutations of the gene (MMAB) encoding for the enzyme ATP:cob(I)alamin adenosyltransferase (ATR, EC 2.5.1.17)." (PMID 32660097, 2020).
multiple sclerosis (7 papers, 2012 to 2022). A progressive autoimmune disorder affecting the central nervous system resulting in demyelination. "Loss of cblb expression renders animals susceptible to autoimmunity, and variants within the CBLB gene are associated with multiple sclerosis in humans." (PMID 22962608, 2012). "CBLB plays a critical role in antigen-induced immune tolerance and Cblb-deficient mice immunized with myelin basic protein are more susceptible to experimental autoimmune encephalomyelitis (EAE), a model for multiple sclerosis." (PMID 23036268, 2012).
leukemia (6 papers, 2015 to 2024). A malignant (clonal) hematologic disorder, involving hematopoietic stem cells and characterized by the presence of primitive or atypical myeloid or lymphoid cells in the bone marrow and the blood. "Many research demonstrated the role of CBLB in leukemia, while PSMC5 and PSMD11 were only reported to be involved in cancer development in very recent studies." (PMID 31874600, 2019). "Interestingly, CBLB, which is the potential downstream target of GATA3 in leukemia as well as LCLs according to our results, contains one SNP (i.e., rs4894953) in its enhancer region." (PMID 28415601, 2017).
colon cancer (5 papers, 2017 to 2023). "Mechanistically, GABA promoted the expression of miR-223-3p in colon cancer cells, and miR-223-3p negatively regulated E3 ligase CBLB." (PMID 38105184, 2023). "Immunofluorescence results also indicated that downregulating the expression of CBLB promoted the proliferation and migration of colon cancer cells." (PMID 38105184, 2023). "It was found that the degradation rate of the cMYC protein was significantly faster when CBLB was overexpressed in colon cancer cells, compared to the cMYC protein, which was considerably slower when CBLB was downregulated." (PMID 38105184, 2023). "MiR-223-3p negatively regulates the expression of CBLB and reduces the ubiquitination degradation of cMYC, thus enabling the proliferation and migration of colon cancer cells." (PMID 38105184, 2023). "This study uncovered that the CBLB expression in colon cancer tissues is low and negatively correlated with their proliferation and migration." (PMID 38105184, 2023). "GABA can reduce the post-transcriptional modification of cMYC protein by CBLB through miR-223-3p, which maintain the stability of cMYC protein and promote the proliferation and migration of colon tumors." (PMID 38105184, 2023). "WB analysis results showed that sleep-deprivation decreased the expression of CBLB in subcutaneous colon cancer tumors, while cMYC was highly expressed in subcutaneous colon cancer tumors of SD group." (PMID 38105184, 2023). "Our data suggests that GABA induces miR-223-3p overexpression, thereby enhancing the stability of cMYC protein in colon cancer cells by downregulating CBLB expression." (PMID 38105184, 2023). "We also identified an endogenous miR-223-3p downregulation of the E3 ligase CBLB, which enhances the stability of cMYC protein and augments colon cancer cells proliferation and migration ability." (PMID 38105184, 2023). "We further explored the polyubiquitinated form of endogenous cMYC in CBLB knockdown colon cancer cells." (PMID 38105184, 2023). "We further explored the effect of the miR-223-3p/CBLB/cMYC axis on colon cancer by another rescue experiment." (PMID 38105184, 2023). "We also detected the expression of CBLB in subcutaneous colon cancer tumors of control group and SD group." (PMID 38105184, 2023). "While MG132 treating CBLB overexpressed colon cancer cells, it showed consistent results." (PMID 38105184, 2023). "Finally, we conducted a rescue experiment to verify the miR-223-3p/CBLB/cMYC axis involvement in mediating the effects of GABA on colon cancer." (PMID 38105184, 2023). "Overexpression of CBLB significantly decreased the expression of cMYC and inhibited the proliferation and migration of colon cancer cells, while GABA was able to rescue the inhibitory effect of overexpression of CBLB on the proliferation and migration of tumor cells." (PMID 38105184, 2023). "Following, we verified the function of CBLB in colon cancer." (PMID 38105184, 2023). "Our results suggest that sleep deprivation can promote the expression of miR-223-3p in colon cancer cells through GABA, leading to downregulation of the E3 ligase CBLB and inhibition of cMYC ubiquitination." (PMID 38105184, 2023). "However, MG132 did not significantly increase the expression of cMYC in CBLB knockdown colon cancer cells." (PMID 38105184, 2023).
lymph node metastasis (5 papers, 2014 to 2020). "CBLB expression is positively associated with early-stage tumor and negatively with lymph node metastasis." (PMID 30111747, 2018). "CBLB could repress IGF-1R and decrease the risk of developing lymph node metastasis in patients with GC." (PMID 30111747, 2018).
type 1 diabetes (5 papers, 2011 to 2022). "Previous studies have linked polymorphisms in two of these genes to Type 1 diabetes (CBLB and SH2B3)." (PMID 24728409, 2014). "Komeda diabetes-prone rats, which are a spontaneous animal model of human type 1 diabetes, as well as CBLB-deficient mice, have been observed to have infiltrations of lymphocytes into pancreatic islets, the thyroid gland, and kidneys, suggesting that CBLB dysfunction leads to autoimmune processes." (PMID 34006268, 2021).
asthma (4 papers, 2012 to 2021). "Of these ten, variants in three genes (PDE4DIP, CBLB, and KALRN) were deemed of particular interest based on their functional prediction scores and previously reported function or asthma association." (PMID 23046476, 2012). "Three of these genes (PDE4DIP, CBLB, and KALRN) are of increased interest based on either their function or previous work in asthma." (PMID 23046476, 2012).
atherosclerosis (4 papers, 2020 to 2024). A disease characterized by the build-up of fatty material and calcium deposition in the arterial wall resulting in partial or complete occlusion of the arterial lumen. "Studies have shown that CBLB can affect the activity of toxic T cells in atherosclerosis." (PMID 38827298, 2024).
colorectal cancer (4 papers, 2016 to 2023). A primary or metastatic malignant neoplasm that affects the colon or rectum. "Moreover, 3/4 driver-downregulated genes showed at least weak evidence of TSG role in the matched tissue (MED12 in brain, SF3B4 in breast, and CBLB in colorectal cancer), with the remaining 1 gene being classified as CGC TSG (CLTC)." (PMID 36625266, 2023). "Together, the potential combined effect of modulation of macrophages via efferocytosis and T-cells via PD-L1 expression, prime a favorable tumor-microenvironment raising the importance of dysregulation of CBL, CBLB, XKR4 and ANO5 in colorectal carcinoma." (PMID 30429477, 2018).